CASP9 (caspase 9)
Diseases named in the same sentence as CASP9 in open-access papers (continued):
Sharing a sentence is not in itself a finding about the gene and the disease.
gastric cancer (continued). "The ROS accumulation in cells can permeabilize the mitochondrial membrane and induce the leakage of proteins to cells to activate the caspase 9 cascade, leading to apoptosis of breast and gastric cancer cells in a mitochondrial-dependent pathway." (PMID 28672882, 2017). "Meanwhile, Caspase 3 inhibitor ZDEVD-FMK and Caspase 9 inhibitor ZLEHD-FMK also strongly inhibited SHK-induced apoptosis of SGC-7901 gastric cancer cells." (PMID 27905569, 2016). "Beclin 1 promoted the apoptosis induced by the chemotherapeutic drug CDDP in the MKN28 human gastric cancer cell line by enhancing caspase 9 activity." (PMID 24675697, 2014). "Furuya found that Beclin 1 can promote the apoptosis induced by the chemotherapeutic drug cis-diamminedichloroplatinum (CDDP) in the MKN28 human gastric cancer cell line by enhancing the caspase 9 activity." (PMID 24675697, 2014). "Our previous studies revealed that the expression of cleaved caspase-9 was significantly lower in colorectal carcinoma than in gastric carcinoma (P<0.0001)." (PMID 25364431, 2014). "In our experiment, increasing levels of Caspase-9 and down-regulation of Bcl-2 and Bcl-xL were detected in human gastric cancer cells, indicating that knockdown of AP-4 activated both intrinsic and extrinsic pathways to apoptosis in cancer cells." (PMID 22615908, 2012). "Caspase 9, an important player in the initiation of the intrinsic apoptosis pathway, is frequently phosphorylated at Thr125 by the mitogen-activated protein kinase (MAPK) pathway, leading to inhibition of caspase 9 activation and caspase 9-mediated apoptosis in gastric carcinoma." (PMID 39860065, 2025). "In this study, after treatment of gastric cancer cells with l,2,3,6-tetra-O-galloyl-β-D-glucose for 24 h, the expression of caspase-9 in the cytosol was increased and caspase-3 was cleaved, indicating that the cell mitochondrial apoptosis pathway was activated." (PMID 35653387, 2022). "Iridoids of valtrate, didrovaltrate, and baldrinal could induce apoptosis of MKN-45 gastric cancer cells, which might be related to increased expression of caspase-3 and caspase-9 in MKN-45 gastric cancer cells." (PMID 36210806, 2022). "We observed the highest percentage of AGS gastric cancer cells with active caspase-8 and caspase-9." (PMID 34770912, 2021). "The molecules, mcl1 and Bcl-xL, inhibit the proliferation of gastric cancer cells and promote apoptosis and then increase the level of miR-133–3p that regulates the antiapoptotic molecules (Caspase-9 and Bcl-xl) to inhibit cell proliferation and promote apoptosis." (PMID 33763149, 2021). "In addition, the activation of cleavage of PARP and caspases, such as caspase-9, -7, -3, has been observed after the treatment of gastric cancer cells with PL." (PMID 33167519, 2020). "The novel diisoquinoline derivatives led to higher expression of caspase-9 in gastric cancer cells." (PMID 29549610, 2018). "Moreover, oridonin treatment induced cell apoptosis, increased the levels of activated caspase-3 and caspase-9, and decreased the mitochondrial membrane potential in gastric cancer cells in a concentration-dependent manner." (PMID 26980707, 2016). "In addition, we also observed a significant increase in activation of caspase-9 and caspase-3 in gastric cancer cells expressing UL138." (PMID 26735338, 2016). "We found the transduction with ATOH1 increased the level of cleaved-caspase-3 and—caspase-9 in GCSCs and gastric cancer cell lines, suggesting that the intrinsic apoptosis pathway might be involved." (PMID 25950549, 2015). "Furthermore, evodiamine raised the ratio of Bax/Bcl-2 in gastric cancer cells, which might lead to activate caspase-9, consequently inducing apoptosis." (PMID 36135210, 2022). "In the treatment of gastric cancer, the alkali upregulated the caspase cascade proteins (cleaving PARP, caspase-3, and caspase-9) and inhibited the phosphorylation of Akt/mTOR, resulting in significant apoptosis of human gastric cancer cells." (PMID 35684449, 2022).
gastric cancer (continued). "We next examined the expression of apoptotic-related factors and found that pro-apoptotic markers (cleaved PARP, cleaved caspase-9, cleaved caspase-3 and Bax) were markedly elevated in G3BP1-compromised gastric cancer cells." (PMID 32989225, 2021). "In this study, we found that FKB promoted the expression of caspase-3, caspase-7, caspase-8, and caspase-9, suggesting that FKB may accelerate the apoptosis of gastric cancer cells partly through the mitochondrial pathway." (PMID 35879950, 2022). "Also, TIPE2 is reported to elicit cell apoptosis by activating caspase three and caspase 9, inducing the cleavage of PARP, and inhibiting bcl-2 expression in BGC-823 gastric cancer cells." (PMID 34630074, 2021). "Subsequently, western blotting showed that LH could also induce the up-regulation of apoptosis-related proteins, C-Caspase 9, C-Caspase 3 and C-PARP in BCL2-drug-resistant gastric cancer cell lines with a dose and time gradient effect." (PMID 33126914, 2020). "In gastric cancer (GC), evidence suggests the involvement of an exo-miR-15b-3p/DYNLT1/Caspase-3/Caspase-9 regulatory network in the pathogenesis." (PMID 38298209, 2024). "In gastric cancer (GC), DYNLT1 takes part in the miR-15b-3p/Caspase-3/Caspase-9 signaling pathway to promote malignant transformation." (PMID 37081842, 2023). "In the western blot assays, PF-induced apoptosis via caspase-9 and caspase-3 cleavage and Z-VAD-FMK blocked the inhibition of cell viability, the induction of LDH and caspase-3 activity, and caspase-3 cleavage in PF-treated AGS and SNU-638 gastric cancer cells." (PMID 38140352, 2023). "As a result, it was confirmed that KU15176 could cause the increasing expression of apoptosis-related genes (Bax, caspase-3, and caspase-9), DNA breakage, effective apoptosis rate, and increased caspase activity in the human stomach adenocarcinoma (AGS) gastric cancer cell line." (PMID 35456891, 2022). "THD has cytotoxic effect on Gastric cancer (GC) cell lines NCI-N87 and AGS, inhibiting colony formation ability, and induces nuclear fragmentation and apoptosis in a caspase-dependent manner through downregulation of caspase-9, caspase-8, and caspase-3 precursors." (PMID 32923398, 2020). "Significant cleavage of caspase 9, caspase 3 and its substrate protein, poly (ADP‐ribose) polymerase (PARP), were detected in SGC7901 cells following JS‐K stimulation, indicating that JS‐K initiated caspase signalling pathway activation in gastric cancer cells." (PMID 30672108, 2019). "To clarify whether the up-regulation of PTEN by TQ and cisplatin led to the apoptosis of gastric cancer cells via mitochondrial pathway, we detected the levels of Bcl-2, Bax, procaspase-9, procaspase-3, Cyt C, AIF, cleaved caspase-9, cleaved caspase-3 using western boltting." (PMID 29156767, 2017). "Therefore, caspase-8 or caspase-9 inhibitor alone did not strongly affect apoptosis of AGS gastric cancer cells." (PMID 22963678, 2012).
glioma (61 papers, 2002 to 2025). A benign or malignant brain and spinal cord tumor that arises from glial cells (astrocytes, oligodendrocytes, ependymal cells). "The down-regulation of anti-apoptotic protein Bcl-2 and activation of caspase 9/3-dependent pathway were associated with tumor cell growth inhibition, especially in glioma cells." (PMID 24303074, 2013). "Variants of CASP9 have shown a strong association with glioma." (PMID 35741587, 2022). "Since miR-211 and pM treatments caused increased apoptosis via caspase-9/3 activation in glioma cells and CSC, we examined the apoptotic DNA laddering profile of miR-211- and pM-treated glioma CSC alone or after subjecting them to a sublethal dose of temozolomide." (PMID 23183822, 2012). "In glioma, miR-181a-5p upregulation promotes G1-phase arrest by targeting caspase-9, Bcl-2, and SIRT1, ultimately inhibiting cell proliferation." (PMID 40863219, 2025). "Utilizing “shORC6-s1” and “shORC6-s2” to knock down ORC6 or employing the CRISPR/Cas9 method to KO ORC6 led to increased caspase-3 and caspase-9 activities within P1 glioma cells." (PMID 38971772, 2024). "In the study, the mRNA and protein levels were demonstrated that many clinical samples’ expression of CASP9 was significantly upregulated in glioma." (PMID 35964070, 2022). "In vitro, activation of CASP9 impairs glioma cell invasion and angiogenesis, and overexpression of CASP9 in combination with radiation has a synergistic effect on glioma invasion inhibition." (PMID 35964070, 2022). "Previously, a prognostic model comprising three PRGs (CASP4, CASP9, and NOD2 (encoding nucleotide binding oligomerization domain containing 2)) was constructed to predict the outcomes of patients with glioma." (PMID 36119521, 2022). "Previously, enhancement of caspase-9 transcript expression upon Cd challenge was reported in the rat glioma C6 cells." (PMID 35911686, 2022). "For example, TUG1 can promote tumor cell apoptosis and inhibit the growth of glioma by activating caspase 3- and caspase 9-mediated proapoptosis, inhibiting bcl-2 mediated antiapoptosis." (PMID 33747256, 2021). "Gefitinib has been reported to induce apoptosis in glioma cells by activating the pro-apoptotic protein Bad, with the ensuing mitochondrial translocation of Bax and the activation of caspase-9, which activates caspase-3." (PMID 30486451, 2018). "SAHA or/and MG132 induced apoptosis in the glioma cells was attributable to the down-regulation of Bcl-2 protein levels and the up-regulation of 14-3-3, Bax, Caspase 9, Capase 3 expression via extrinsic and intrinsic pathways." (PMID 27911270, 2017). "Our data indicated that levels of the activated form of caspase-9 were significantly higher in glioma cells treated with Ad-SGE-REIC than in those treated with Ad-CAG-REIC and control." (PMID 27625116, 2016). "The data demonstrate a direct involvement of BIM in the induction of the caspase-9 driven apoptotic pathway in glioma cells following TMZ and ACNU treatment." (PMID 26418950, 2015).
glioma (continued). "Similar with the results of glioma cells, shikonin or topotecan significantly reduced the expression of Bcl-2 as well as promoted the activation of caspase-9 and caspase-3 in GSCs-U251 and GSCs-U87 cells respectively, compared to the control groups (P<0.01)." (PMID 24303074, 2013). "The siRNA-mediated knockdown of MMP-9 expression has also been shown to induce Caspase-9-mediated apoptosis in glioma cells." (PMID 23183822, 2012). "In independent experiments, we confirmed that miR-211 overexpression and pM treatments led to the activation of the intrinsic mitochondrial/Caspase-9/3-mediated apoptotic pathway in both glioma cells and cancer stem cells (CSC)." (PMID 23183822, 2012). "Furthermore, molecules like Gefitinib is reported to induce apoptosis in human glioma by affecting the BAD/BAX signaling pathway including activating caspase 9/3." (PMID 39833890, 2025). "Subsequent studies unveiled a significant decrease in the mRNA and protein expression levels of Cyclin A2, Cyclin B2, and TOP2A within koORC6 P1 glioma xenograft tissues, where elevated levels of cleaved-caspase-3, cleaved-caspase-9, and cleaved-PARP-1 were detected, indicating apoptosis activation." (PMID 38971772, 2024). "Additionally, the levels of cleaved forms of caspase-3 (Clvd-caspase-3) and caspase-9 were elevated in ORC6-silenced/-KO P1 glioma cells." (PMID 38971772, 2024). "Additionally, small nucleolar RNA host gene 16 (SNHG16) suppressed the expression of p21, caspase-3 and caspase-9, while promoting cyclin-D1 and cyclin-B1 expression to inhibit apoptosis in glioma cells." (PMID 35601497, 2022). "Similarly, the combined treatment (As+Cd+Pb) in individual lethal concentration (LC)-5 induced a toxic effect on C6-glioma cells derived from rat glioma, via mitochondria-mediated apoptosis, including caspase-9 activation and Bax/Bcl-2 changes." (PMID 34204190, 2021). "In fact, a chemotherapy drug previously used to treat brain tumor called etoposide, a topoisomerase II inhibitor, actually mediates glial apoptosis in the C6 glioma cell line via the ceramide pathway by inducing the release of cytochrome c, and leading to the activation of caspase-9 and caspase-3." (PMID 29348854, 2017). "Juglone could obviously inhibit the proliferation of TSCs in glioma by decreasing cell viability (P < 0.01) and inducing apoptosis (P < 0.01), which was accompanied by increased caspase 9 cleavage in a dose-dependent manner (P < 0.01)." (PMID 28388894, 2017). "Moreover, the upregulation of the proapoptotic genes: Bim, Bax, Puma, Noxa and increased activity of caspase-9 were observed in LBC3 glioma cells." (PMID 28825685, 2017). "Similarly, ceramide has been reported to cause apoptotic cell death by altering the Bax/Bcl2 ratio which triggers cytochrome C release from the mitochondria and results in activation of the caspase-9/-3 cascade in C6 glioma cells." (PMID 22973882, 2012).
glioma (continued). "Moreover, Sch B induces cell cycle arrest of glioma cells in the G0/G1 phase, triggers apoptosis through the activation of caspase-3, caspase-9, poly (ADP-ribose) polymerase (PARP), and Bcl-2, and significantly inhibits the tumor growth of glioma cells in vivo." (PMID 39995410, 2025). "According to previous studies, treatment with curcumin in human U87 glioma cells was able to downregulate miRNA-21 expression by antisense oligonucleotides, inhibit glioma cell proliferation, and induce cell apoptosis through activation of caspase-3 and caspase-9." (PMID 38303058, 2024). "However, CASP9 showed lower expression levels in the 3 glioma cell lines, which we consider might be due to variations in the microenvironment between tumor cells cultured in vitro and tumor tissues." (PMID 35964070, 2022). "In addition, we found that in glioma tissues from the TCGA database, SAA1 levels were associated with a range of anti-apoptotic genes (Bcl-xl, BFL1, MCL1, BIRC5, and Fas) and pro-apoptotic genes (Bim, Bid, CASP9 and Apaf1)." (PMID 33854635, 2021). "We found that the human H4 glioma cell-killing effects of aspirin involved mitochondria-mediated apoptosis accompanied by endoplasmic reticulum (ER) stress, Noxa upregulation, Mcl-1 downregulation, Bax mitochondrial distribution and oligomerization, and caspase 3/caspase 8/caspase 9 activation." (PMID 32545774, 2020). "However, several literatures report that caspase 9-mediated intrinsic pathways could be induced by Licochalcone A in other cell types such as glioma stem cells, and nasopharyngeal carcinoma cells." (PMID 31269698, 2019). "Shikoinin could increase caspase 3, caspase 8 and caspase 9 activities in glioma cells." (PMID 24714453, 2014). "Levels of pro-apoptotic proteins (including Bad and cleaved-caspase-9) were increased, while the expressions of anti-apoptotic markers(e.g., MMP-9, MMP-2, and Bcl-2) were decreased in PQR309-treated glioma models." (PMID 38555280, 2024). "Caspase-3, caspase-9 and poly (ADP-ribose) polymerase-1 (PARP) cleavages were induced in Gαi2-silenced/KO P1 glioma cells, and levels of histone-bound DNA were augmented." (PMID 36778118, 2023). "Western blot assay revealed that TSAIII significantly increased the expression of cleaved-caspase-3 (c-caspase-3), cleaved-caspase-9 (c-caspase-9), and cleaved-caspase-PARP (c-PARP) in both glioma cell lines (p < 0.01 as compared to control)." (PMID 36611961, 2022). "In glioma, TUG1 functions as a tumor suppressor by promoting cell apoptosis via activating caspase-3 and caspase-9 mediated intrinsic pathways and inhibiting Bcl-2 mediated anti-apoptotic pathways." (PMID 35601497, 2022). "Compared with HA 1800 and HMC3 cell lines, the expression levels of CASP4, CASP9 and GSDMC showed an overall upward trend, and the IL1A level showed an overall downward trend in glioma cell lines." (PMID 35547808, 2022). "On probing the initiator caspases, both caspase 8 (extrinsic or ligand mediated pathway) and caspase 9 (intrinsic or mitochondrial pathway), we observed that neither of these caspases were activated upon AEBP1 down regulation in U138MG glioma cells." (PMID 31601918, 2019). "In our study, the results showed that flubendazole increased apoptosis among glioma cells via downregulating the expression of Bcl-2, Bcl-xl, and PARP-1, while upregulating the expression of caspase-3, caspase 6 and caspase-9." (PMID 29531815, 2018). "Sch B induces cell apoptosis by increasing Bax, cleaved caspase-9, cleaved caspase-3, and cleaved PARP and reducing Bcl-2 protein expression in glioma cells." (PMID 25685066, 2015).